AR (androgen receptor)
Diseases named in the same sentence as AR in open-access papers (continued):
Sharing a sentence is not in itself a finding about the gene and the disease.
prostate carcinoma (continued). "Androgen-activated androgen receptor has been linked to prostate cancer progression, thus steroid drugs structurally similar to but different from androgens are clinically used to block androgen activation and to treat prostate cancers." (PMID 36459502, 2022). "We report the inverse association between the expression of androgen receptor (AR) and IL1β in a cohort of patients with metastatic castration-resistant prostate cancer." (PMID 36561929, 2022). "AR mutations have been widely studied in the context of prostate cancer and are associated with resistance to anti-androgen therapy." (PMID 35173303, 2022). "An increase in the AR/SGTA ratio in metastatic prostate cancer cells, as compared to primary PCa tumor cells, can cause the reduced control of AR function, and thus exacerbate PCa progression through the receptor." (PMID 35055079, 2022). "The activities of MYC, the androgen receptor, and its associated pioneer factors demonstrate substantial reprogramming between early and advanced prostate cancer." (PMID 36181613, 2022). "The expression of androgen receptor variants (AR-Vs) is associated with the development of advanced castration-resistant prostate cancers (CRPCs), while prostate cancer stem cells (PCSCs) have been evaluated as the most dangerous malignant seeding cells." (PMID 36428807, 2022). "Nonetheless, in prostate cancer cells, AR variants also partition into transcriptional condensates, which have been shown to alter the expression of target gene products." (PMID 36388907, 2022). "Prostate cancer is driven by androgen receptor-regulated transcription and is a leading cause of cancer deaths." (PMID 36291932, 2022). "This is accompanied by the loss of DNA binding of several key transcription factors in prostate cancer progression, including the AR, FOXA1 and ERG." (PMID 36212399, 2022). "ERG (E-26 transformation-specific-related gene) is another gene implicated in AR-signaling in prostate cancer through microtubule depolymerization." (PMID 35884386, 2022). "The combination of rucaparib with AR has been approved to guide therapy based on paclitaxel harmful BRCA mutations in patients with metastatic castration-resistant prostate cancer." (PMID 36010882, 2022). "For example, RNF6 mediates K27-linked polyubiquitination of the androgen receptor (AR), thereby recruiting the chaperone proteins to increase the oncogenic transcriptional activity of AR in prostate cancer." (PMID 35926709, 2022). "Technological advancements in the past two decades revealed that residual androgens, ADT-induced AR splice variants, and AR mutations are common mechanisms of metastatic castration-resistant prostate cancer." (PMID 36010882, 2022). "Following the evidence that AR interacts with SMAD proteins in prostate cancer, we proposed that SMAD4 dynamically associates with AR to orchestrate specific gene expression programmes in a time- and context-dependent fashion." (PMID 35522298, 2022). "For example, the DEG, LINC02532, was recently identified as a marker of radiosensitivity in clear cell renal carcinoma, while ARLNC1, decreased in our data, is associated with maintenance of androgen receptor signalling in prostate cancer." (PMID 36233808, 2022). "We next inquired about the reason that constitutively active AR variants that are linked to castration‐resistant prostate cancer, the most aggressive stage of the disease, lose their repressive capacities." (PMID 34919781, 2022). "EPI-7386 inhibits cell proliferation across a panel of prostate cancer cell lines, including those driven by the AR variant AR-V7, can control tumor growth and induce tumor regression in several CRPC xenograft models, and is well tolerated in animal models." (PMID 35864113, 2022).
prostate carcinoma (continued). "Whilst the nuclear receptor transcription factor, androgen receptor, drives the growth of prostate tumor during initial stage of the disease, androgen resistance is associated with poorly differentiated prostate cancer." (PMID 35547880, 2022). "Major adaptations of prostate cancer to the inhibition of AR signaling are counterbalanced enhancement of AR signaling through AR overexpression, gene amplification, activating mutations, and expression of ligand-independent variants." (PMID 36194476, 2022). "Two lncRNAs, PRNCR1 and PCGEM1, are found to be overexpressed in different prostate cancers and cause the androgen receptor (AR)–associated transcriptional mechanisms to induce the growth of prostate cancer." (PMID 36359888, 2022). "AR alternative splice variants (AR-Vs) are involved in the progression of prostate cancer bone metastasis." (PMID 35812177, 2022). "Several splicing factors have been found to be associated with alternative splicing events in the AR precursor mRNA (pre-mRNA) in prostate cancer cells." (PMID 35454821, 2022). "An increase in microvascular infiltration is associated with prostate cancer metastasis through AR signaling." (PMID 35317831, 2022). "Ligand-independent androgen receptor splice variants emerge during androgen deprivation therapy and are suspected to render prostate carcinomas castration-resistant." (PMID 36139600, 2022). "SRC-2 is a NCoA of the androgen receptor (AR) and is highly associated with poor survival in prostate cancer." (PMID 36582250, 2022). "There are well-known differences in the lengths of CAG and GGN repeats in AR among race/ethnic groups associated with differences in transcriptional trans-activation and correlated with prostate cancer risk." (PMID 35104804, 2022). "To date, various mechanisms of resistance have been identified including the development of AR-independent aggressive variant prostate cancer based on neuroendocrine transdifferentiation (NED)." (PMID 35109899, 2022). "Overexpression of AKR1C3 is usually associated with prostate cancer progression, aggressiveness, and resistance to AR-targeted therapies." (PMID 35646665, 2022). "Most notably, AR is a major driver of prostate cancer (CaP) progression, which remains the second leading cause of cancer deaths in American men." (PMID 35326387, 2022). "Drives prostate cancer cell proliferation; maintain prostate cancer cell survival; mutation and amplification of AR in prostate cancer contributes to androgen deprivation therapy resistance." (PMID 35547880, 2022). "Although second-generation AR antagonists have prolonged prostate cancer survival time, side effects and the rapid evolution of drug resistance remain stumbling blocks associated with the use of AR antagonists in clinical practice." (PMID 35864113, 2022). "Variation in the AR gene has been associated with male reproductive function, cardiovascular health, prostate cancer, bone density, muscle mass, level of testosterone, and rate of change in testosterone with increasing age." (PMID 36418656, 2022). "Prostate cancer is the most common cancer among men, and the androgen receptor (AR) plays a central role in its progression by regulating the expression of genes associated with the identity and behavior of prostate cancer cells." (PMID 35103065, 2022). "It was shown to be a potent anti-prostate cancer agent that inhibited the function of androgen receptor (AR) splice variants, potentially through interaction with the AR DNA-binding domain (DBD), and the inhibition of several splicing factors (such as DDX17)." (PMID 36552005, 2022). "One of the aggressive variants of prostate cancer that are AR independent is neuroendocrine prostate cancer (NEPC)." (PMID 35582526, 2022). "It is well known that human prostate cancer 22Rv1 cells are resistant to hormone therapy because of the expression of the androgen receptor splice variants AR-V7." (PMID 36364202, 2022).
prostate carcinoma (continued). "We assessed expression of the androgen receptor, a frequently overexpressed driver of prostate cancer, and of its AR-V7 splice variant, which is associated with clinical ENZ-resistance." (PMID 36348939, 2022). "Germline mutations can lead to the androgen insensitivity syndrome while somatic mutations often arise as a response to hormone therapy for prostate cancer (PCa), thus leading to resistance to AR-targeting therapies." (PMID 35163481, 2022). "RON is highly expressed in castrate-resistant prostate cancer and is activated following androgen deprivation to compensate for the loss of AR expression." (PMID 35454943, 2022). "It is known that the imbalance of the AR activation state is the main cause of the development of prostate cancer." (PMID 36482936, 2022). "Prostate-cancer-associated fibroblasts play an important role in promoting tumor progression and therapeutic resistance to androgen-receptor-signaling inhibitors, such as enzalutamide." (PMID 35884514, 2022). "Activation of the androgen receptor (AR) and its splice variants is linked to advanced prostate cancer and drives resistance to antiandrogens." (PMID 36555754, 2022). "The SUMO protease SENP1 was identified as a factor that promotes the removal of C-terminal SUMO moieties from human HDAC1 in a prostate cancer model, causing upregulation of the androgen receptor." (PMID 34003109, 2021). "Although somatic AR mutations are rarely detected in early-stage prostate cancer, mutation frequency is significantly increased in advanced androgen-independent tumors, suggesting that AR mutations have a role in tumor progression." (PMID 34298822, 2021). "Androgen deprivation therapy (ADT) for metastatic and high-risk prostate cancer (PC) inhibits growth pathways driven by the androgen receptor (AR)." (PMID 34680353, 2021). "Resistance to drug treatments is common in prostate cancer (PCa), and the gain-of-function mutations in human androgen receptor (AR) represent one of the most dominant drivers of progression to resistance to AR pathway inhibitors (ARPI)." (PMID 34208290, 2021). "Activation of the PI3K/Akt pathway and androgen receptor (AR) generates reciprocal feedback in PTEN-deficient prostate cancer." (PMID 34026624, 2021). "Long intergenic non-coding RNA (lincRNA) PVT1 is an overexpressed oncogene that is associated with AR in LNCaP prostate cancer cells, and with PRC2 in HeLa and many other types of cancer cells." (PMID 33430890, 2021). "In prostate cancer, the incorporation of H2A.Z is a requisite for activation of androgen receptor-associated enhancers." (PMID 35317119, 2021). "AR mutations, Post-Translational Modifications (PTMs), over-expression and splice variants were some of the ways through which prostate cancers evaded Androgen Ablation Therapy (AAT)." (PMID 34062779, 2021). "In the androgen-sensitive prostate cancer cell line LNCaP, Tip60 knockdown causes localisation of AR in the cytoplasm, which subsequently decreases PSA expression." (PMID 34381019, 2021). "Epigenomic annotation of GWAS SNPs associated with prostate cancers revealed that two out of nine SNPs within prostate enhancer regions destroyed putative androgen receptor (AR) binding motif." (PMID 34513844, 2021). "AR forms with constitutive activity are known for prostate cancer; for example, the AR-Vs (variants) are located mainly in the nucleus (also in breast cancer lines like MDA-MB453) and present constant activity." (PMID 34638264, 2021). "IL-6 activation of the androgen receptor in some prostate cancers is associated with increased growth in vitro and in vivo." (PMID 34204596, 2021). "Among the concordant downregulated genes is FLNA, encoding filamin A, which is a regulator of the androgen receptor in prostate cancer." (PMID 34316327, 2021).
prostate carcinoma (continued). "A direct association of Ku70/Ku80 with AR has already been reported for prostate cancer cells, in which, however, Ku70 and Ku80 were implicated in control of AR-dependent transcription, rather than AR being required for Ku70/Ku80 association with RNA Pol II." (PMID 33112375, 2021). "Mutations in the RNF6 gene and specific inhibition change AR transcriptional activity in xenograft models and delay the progression of prostate cancer." (PMID 34081837, 2021). "CWR22Rv1 prostate cancer cells that express both AR and AR variants were treated with the newly synthezied compounds as indicated (1 μM for 16 h)." (PMID 34272475, 2021). "A reduction in AR-induced miR-203 levels has been associated with an increased growth and migration potential of prostate cancer cells." (PMID 34831421, 2021). "A reciprocal relationship has been demonstrated between androgen receptor (AR) and Akt pathways in preclinical prostate cancer models with PTEN loss, such that inhibition of one leads to up-regulation of the other." (PMID 35011901, 2021). "Earlier researchers have observed that Qu provokes prostate cancer by decreasing expression of androgen receptor (AR), by causing apoptosis and repressing proliferation." (PMID 33804548, 2021). "The overexpression of this gene promotes androgen receptor activity and is associated with prostate cancer progression." (PMID 33672425, 2021). "Tumor hypoxia increases AR signaling and is associated with treatment resistance in prostate cancer." (PMID 33671134, 2021). "KDM4C overexpression is associated with poor prognosis in prostate cancer and can co-regulate transcriptional activation of the AR." (PMID 34220955, 2021). "A downstream effector of the β-catenin pathway was shown to be an androgen receptor co-activator, which is an oncogene and implicated in prostate cancer." (PMID 35201496, 2021). "We now report that prostate cancer associated fibroblasts express a transcriptional-incompetent androgen receptor." (PMID 33500395, 2021). "MYC is one of the most highly expressed genes in prostate cancer, and has been shown to positively regulate the AR and its splice variants." (PMID 35008216, 2021). "Prostate cancer mainly relies on AR mutations, overexpression and changes of related cofactors to adapt to survival, thus becoming CRPC." (PMID 33946224, 2021). "IRE1α formed a positive feedback loop with IL-6 and AR to promote prostate cancer cell proliferation under the androgen-deficient condition." (PMID 34295814, 2021). "Mutation or polymorphisms of the androgen receptor in African American PCa patients are associated with an elevated prostate cancer risk." (PMID 34316327, 2021). "Acting together, they change the transcriptional output of prostate cancer cells and lead to the loss of luminal and epithelial markers, such as AR, and the increase in the expression of basal and neuroendocrine-related genes." (PMID 33420371, 2021). "Prostate cancer expresses various truncated AR variants that lack the C-terminal domain through aberrant splicing regulation." (PMID 33923658, 2021). "Aberrant activation of androgen receptor (AR) signaling is one of the main causes by which prostate cancer acquires castration resistance." (PMID 33997443, 2021). "Our results suggest that induction of WNT4/TCF7L1 results in increased NED and malignancy in prostate cancer that is linked to dysregulation of androgen receptor signaling and activation of the IL-8/CXCR2 pathway." (PMID 34799554, 2021). "Androgen receptor splice variants (AR-Vs) play an important role in prostate cancer progression, especially as a putative resistance mechanism against AR-targeted therapies." (PMID 34071114, 2021). "This study revealed heterogeneous expression levels of the different splice variants between and within prostate cancer patients progressing on an AR inhibitor." (PMID 33448107, 2021).
prostate carcinoma (continued). "Our data demonstrated KIF4A and WDR62 are AR-independent prostate cancer driver genes that are associated with poor prognosis in patients with advanced metastatic disease." (PMID 34326322, 2021). "Small cell carcinoma (SCC)/neuroendocrine prostate cancer (NEPC) is a rare and highly aggressive subtype of prostate cancer associated with an AR(androgen receptor)-null phenotype and visceral metastases." (PMID 34646773, 2021). "Previous reports have shown that c-Jun enhancement of androgen receptor transactivation is associated with prostate cancer cell proliferation." (PMID 33926470, 2021). "As before, we used Western blotting to profile the protein expression patterns of the AR and signaling molecules implicated in prostate cancer on a separate cohort of intact CNPC and vehicle and apalutamide-treated CRPC mice (n = 3 mice)." (PMID 34439133, 2021). "Since the alterations in AR are associated with prostate cancer, the inhibition of AR by drugs is the prevention target for prostate cancer growth." (PMID 33917905, 2021). "ELK-1 protein is known to be a critical partner for the androgen receptor (AR) in prostate cancer, and its expression was found to be associated with a higher clinical stage and prognostic marker of disease recurrence in prostate cancer." (PMID 33671331, 2021). "Nevertheless, AR, the gene encoding the hub with the second largest number of interactions among those in the “prostate cancer” pathway, was strongly downregulated (log2 fold-change −3.5)." (PMID 34768937, 2021). "One possible mechanism by which the prostate cancer becomes resistant to androgen deprivation therapy is alterations in AR, including AR amplification or overexpression, AR mutations and truncated AR lacking ligand-binding domains (ARΔLBD)." (PMID 34630112, 2021). "High mortality rates of prostate cancer (PCa) are associated with metastatic castration-resistant prostate cancer (CRPC) due to the maintenance of androgen receptor (AR) signaling despite androgen deprivation therapies (ADTs)." (PMID 34386489, 2021). "We found lnc-OPHN1-5, which lies close to the androgen receptor (AR) gene on chromosome X, increased prostate cancer (PCa) Enzalutamide (Enz) sensitivity via decreasing AR protein expression and associated activity." (PMID 34545067, 2021). "According to this study, cardiac glycosides block the expression of AR target genes and inhibits the proliferation of androgen-sensitive and androgen-resistant prostate cancer cells by causing AR destabilization." (PMID 34660328, 2021). "The role of PTEN loss in prostate cancer is also highlighted by the reciprocal feedback interaction between the androgen receptor (AR) and the PI3K/Akt pathways." (PMID 34948314, 2021). "AR-v7, a common AR splice variant, increased substantially as patients progressed to castration-resistant prostate cancer." (PMID 33460399, 2021). "Around nine deletion and more than 70 different somatic missense androgen receptor mutations have been described in patients with prostate cancer, with several having gain of function." (PMID 35201496, 2021). "Spearman correlation analysis revealed that NDRG1 pS330 levels in prostate cancer are associated with AR pS213 (r = 0.3664, p = 0.01) and PIM1 protein levels (r = 0.5038, p = 0.00003)." (PMID 33398037, 2021). "Variants in the androgen receptor gene correlate with androgen sensitivity and are implicated in diseases like androgenetic alopecia and prostate cancer, conditions that have been associated with worse COVID-19 outcomes and hospitalization." (PMID 33179220, 2021). "In recent years, there has been an increase in the number of aggressive androgen receptor variant prostate cancers with neuroendocrine characteristics (NEPC) or small cell characteristics (small cell prostate cancer) with low expression or deletion." (PMID 34863188, 2021). "Androgen receptor (AR) and its variants play vital roles in development and progression of prostate cancer." (PMID 33390843, 2021).